STAT3 (signal transducer and activator of transcription 3)
Diseases named in the same sentence as STAT3 in open-access papers (continued):
Sharing a sentence is not in itself a finding about the gene and the disease.
tumor (continued). "While other studies show that IL-17A can promote tumor growth and metastasis through IL-6/Stat3 signaling pathway or through the induction of tumor promoting microenvironment at tumor site." (PMID 21760911, 2011). "Treatment with IFN-α further enhanced the levels of pSTAT1 while decreasing those of pSTAT3 and total STAT3 in tumor cells further altering the balance between the two transcription factors in favor of the pro-inflammatory and pro-apoptotic phenotype." (PMID 21875439, 2011). "Immunohistochemical probes were applied to detect p-mTOR (Ser2448), p-Akt (Ser473), p-ERK1/2 (Thr202/Tyr204), nestin, and p-STAT3 (Tyr 705) in the original and recurrent tumor." (PMID 21494688, 2011). "Cucurbitacin-I (JSI-124) is potent inhibitor of JAK/STAT3 signaling pathway and has anti-tumor activity in a variety of cancer including B cell leukemia." (PMID 21702955, 2011). "Cell Tracker Red was introduced to track MSCs in vivo and ascertain the tumor tropism of Adv-Stat3(-)-loaded MSCs." (PMID 22054049, 2011). "Our data suggest that growth rate of the STAT3-silenced tumor cells in nude mice was significantly reduced compared to control vector cells." (PMID 21991388, 2011). "STAT3 can restrain anti-tumour immune responses and regulate key cancer-promoting inflammatory mediators, which can initiate or promote oncogenic transformation, and genetic and epigenetic changes in malignant cells." (PMID 21806788, 2011). "Transducer and activator of transcription-3 (STAT3) plays an important role in tumor cell invasion and metastasis." (PMID 21991388, 2011). "Reverse transcription -PCR was done to analyze the mRNA level expression of STAT3 in representative soft tissue tumor samples." (PMID 21575192, 2011). "In this report, Src knock-down in combination with the knock-down of the downstream molecules STAT3 or cMyc is shown to result in a strong inhibition of the anchorage-independent growth, tumor growth, and metastasis of a human cancer cell line." (PMID 21541295, 2011). "This is direct evidence to demonstrate STAT3 in monocytes can broadly and profoundly affect tumor growth via stimulation of tumor cell survival and proliferation." (PMID 22136659, 2011). "Simultaneous knock-down of Src and Stat3, and/or Myc exhibited the greatest effects resulting in substantial inhibition of primary tumor growth and metastasis." (PMID 21541295, 2011). "We confirm for the first time that interference with the HGF/c-met/Stat3 signaling pathway can block tumor cell invasion in an in vivo model, and we present evidence for a positive feedback loop between Stat3 and c-met." (PMID 21595927, 2011). "We determined gene expression in these STAT3-knocking down tumors using a human tumor metastasis PCR array (#PAHS-028A) from SuperArray Bioscience." (PMID 21991388, 2011). "STAT1 has been considered generally to be a tumour suppressor, while STAT3 and STAT5 are known to be proto-oncogenes." (PMID 21338529, 2011). "Some researchers have suggested that Th17 cells promote tumor growth through an IL-6/STAT3 pathway, up-regulation of IL-8, and induction of tumor angiogenesis." (PMID 22051182, 2011). "Chemopreventive agents including curcumin operate their inhibiting effects on carcinogenesis by inducing apoptosis of tumor cells via affecting multiple signaling pathways including NF-КB, STAT3, MAPK and Bax induction." (PMID 29147235, 2011). "STAT3 has been shown to activate transcription of many genes involved in oncogenesis, cell survival, tumor progression and metastasis." (PMID 22046235, 2011). "The co-culture experiments evaluated by flow cytometry were repeated with different ratios of MSC/Adv-Stat3(-) in tumor and HUVEC cells." (PMID 22054049, 2011). "Aberrantly hyper-activated STAT3 signaling in cancer cells and in the tumor microenvironment has been detected in a wide variety of human cancers and is considered an important factor for cancer initiation, development, and progression." (PMID 22136659, 2011).
tumor (continued). "Intravenous injection of MSCs carrying Adv-Stat3(-) suppressed the Stat3 pathway, down-regulated Ki67 expression, and recruited CD11b-positive cells in the local tumor, inhibiting tumor growth and increasing the survival of tumor-bearing mice." (PMID 22054049, 2011). "The STAT3 expression in their tumor tissues was examined using the immunohistochemistry (IHC) method, and evaluated for its association with clinicopathological parameters." (PMID 21806788, 2011). "Total levels of Stat3 activity and expression were determined by Western blot analysis of tumor lysates." (PMID 21595927, 2011). "We have demonstrated that these TAMs, which arise from circulating monocytes that are recruited into the tumor microenvironment, can be modulated by the gCSCs by inducing an immunosuppressive phenotype via the STAT3 pathway." (PMID 21283755, 2011). "STAT3 normally resides in the cytoplasm and is often constitutively activated in many human cancer cells and tumor tissues and has been shown to induce expression of genes involved in cell proliferation and survival." (PMID 21575192, 2011). "The clinical significance of IL-17 was authenticated by revealing that the combination of intratumoral IL-17+ cells and phospho-STAT3 served as a better prognosticator for postoperative tumor recurrence than either marker alone." (PMID 22171994, 2011). "Recent work has shown that expression of high levels of STAT3 in human OSA tumor samples correlated to poor differentiation, metastasis, and lower rates of overall and relapse-free survival." (PMID 21443800, 2011). "Tumor-induced maintenance of constitutive STAT-3 activation in DCs eventually results in the acquisition of the tolerogenic potential of these cells." (PMID 22110524, 2011). "Despite its frequent involvement in cancer, which makes it a highly valuable target for inducing tumor cell death, STAT3 still lacks more specific inhibitors." (PMID 21486470, 2011). "In this study, we found that silencing of STAT3 expression suppressed tumor growth and invasion and the microvessel density in nude mice." (PMID 21991388, 2011). "The interplay of STAT3 in cancer cells and immune cells in tumor microenvironment is very complex and remains elusive." (PMID 22136659, 2011). "It has been shown that STAT3 activity and expression is increased in bladder cancer tumor and predicts tumor recurrence and patient survival." (PMID 21408190, 2011). "Tumor invasion into the vessel and muscle was more infrequent in the STAT3-silenced tumors than in control tumors." (PMID 21991388, 2011). "Persistent activation of the STAT3 signaling in murine respiratory epithelial cells was also shown to induce pulmonary inflammation and tumor formation in the lung." (PMID 22194995, 2011). "Of note, predicted within the MSKCC data set tumor suppressor features is the established oncogenic transcription factor STAT3." (PMID 22174824, 2011). "At day 52, the mean tumor volume in the Adv-Stat3(-) group was 248.3 ± 34.2 mm3, which was significantly smaller than that of the PBS (437.9 ± 36.3 mm3) and MSC (485.4 ± 31.6 mm3) groups (P < .05)." (PMID 22054049, 2011). "STAT3 is known to enhance tumor cell invasion, metastasis, and angiogenesis through enhanced expression of VEGF and MMP2." (PMID 21443800, 2011). "The transcription factor STAT3 (signal transducer and activator of transcription 3) is frequently activated in tumor cells." (PMID 21486470, 2011). "STAT3 is a major mediator of tumorigenesis, and has been shown to be vital for tumor cell growth, proliferation, and apoptosis." (PMID 21575192, 2011). "We have previously demonstrated that both canine and human OSA cell lines, as well as 8 fresh canine OSA tumor samples, exhibit constitutive phosphorylation of STAT3, and that this correlates with enhanced expression of matrix metalloproteinase-2 (MMP2)." (PMID 21481226, 2011).
tumor (continued). "In GBM, abnormally activated STAT3 activates a number of downstream genes to regulate multiple behaviors of tumor cells, such as survival, growth, angiogenesis, invasion, and evasion of immune surveillance." (PMID 21906308, 2011). "A number of tumor cell survival proteins, such as phospho-STAT3 Tyr705, phospho-Erk and total Jak1 were up-regulated in A2780 cells after exposure to γδ T cells." (PMID 21935360, 2011). "Next, we injected 1 × 106 Adv-Stat3(-)-loaded MSCs labeled with Cell Tracker Red into the tumor-bearing mice." (PMID 22054049, 2011). "Activation of STAT3 and its target genes can lead to cell-cycle progression, immune evasion, proangiogenesis, antiapoptotic effects, tumor invasion and metastasis, all of which are typical characteristics of cancer." (PMID 21526200, 2011). "IL-17 mediated tumor-promoting role involves a direct effect on HCC cells through IL-6/JAK2/STAT3 induction by activating the AKT pathway." (PMID 22171994, 2011). "Although these observations are particularly pertinent to gastrointestinal tumours, we suggest that the tumour's addiction to persistent Stat3 activation is likely to also impact on other epithelial cell-derived cancers." (PMID 20478049, 2010). "Normal cells, in contrast to tumor cells are relatively tolerant to interruption of the STAT3 signaling pathway, making STAT3 an excellent target for molecular therapy of cancer." (PMID 20840775, 2010). "One member in particular, STAT3, has been shown to be constitutively activated in a number of human tumor cell lines and primary tumors, including several hematological malignancies." (PMID 20433747, 2010). "Signal Transducer and Activator of Transcription 3 (Stat3) is one of the transcription factors that play an important role in tumor cell growth, survival, proliferation, differentiation, apoptosis, metastasis, angiogenesis and drug resistance." (PMID 20459702, 2010). "Aberrant Stat3 activation in tumour cells promotes the secretion of immunomodulatory factors, which selectively reduce the Th1 dominated anti-tumour response." (PMID 20478049, 2010). "In WP1066-treated tumours, on the other hand, there was little p-STAT3 immunostaining (upper right)." (PMID 20461084, 2010). "Collectively, these studies provide precedent for targeting STAT3 as a means of inducing tumor cell apoptosis." (PMID 20576164, 2010). "Accordingly, the extent of lymphocytic Stat3 activation directly shapes the overall tumour immune response including the Treg's capacity to deprive Th17 cells from essential activation cues." (PMID 20478049, 2010). "These two pathways converge in tumour cells and result in activation of the latent signal transducer and activator of transcription 3 (Stat3) which mediates a transcriptional response favouring survival, proliferation and angiogenesis." (PMID 20478049, 2010). "STAT3 is activated in 50-90% of cancers including a majority of melanoma cell lines and tumor samples tested." (PMID 24281185, 2010). "The capacity of Stat3 to modulate the anti-tumour immune response in macrophages and DCs partly depends on the heterodimeric IL12 cytokine family, which directs the outcome of inflammatory processes." (PMID 20478049, 2010). "The candidate substrates identified in our analysis (e.g. p120, integrin β4, plakophilin 3, STAT3 and vimentin) will inform future studies addressing the mechanisms involved in CSF-1R-induced tumor progression." (PMID 21049007, 2010). "STAT3 signaling within the tumor microenvironment was recently elucidated to induce a protumor cytokine, IL-23, while inhibiting a central antitumor cytokine, IL-12, thereby shifting the balance of tumor immunity toward tumorigenesis." (PMID 20885915, 2010). "Stat3 pathway plays an important role in tumor cell growth and proliferation, and is constantly activated in many human cancer cell lines and tumor tissues." (PMID 20459702, 2010).
tumor (continued). "The expression of STAT3C, which mimics the constitutive STAT3 activation observed in many tumours, is thus sufficient to promote aerobic glycolysis, acting at least in part through transcriptional induction of Hif-1α." (PMID 21084727, 2010). "Many proteins that are crucial for tumor cell proliferation and survival have been found to be regulated by STAT3; these include Bcl-2, Bcl-XL, cyclin D1/D2 and IL-6, which are considered to contribute to the anoikis resistance-inducing property of STAT3." (PMID 20507639, 2010). "In contrast, tumour growth was arrested and glucose uptake reduced upon S3I treatment already at 3 days, suggesting that inhibition of STAT3 activity has prominent effects on glucose metabolism also in vivo." (PMID 21084727, 2010). "Perhaps half or more of human tumors have long since been documented to contain persistently active STAT3 and human tumor cell lines depend on STAT3 for continued rapid growth and avoidance of apoptosis." (PMID 21149895, 2010). "Sall4, Grb2, β-catenin, and Stat3 are known to be expressed in tumor cells and their roles in cancer has been already studied." (PMID 20950440, 2010). "Surprisingly, tumour development in gp130Y757F mice is restricted to the glandular stomach despite systemic hyperactivation of endogenous Stat3." (PMID 20478049, 2010). "The ability of FLLL32 to specifically inhibit the STAT3 pathway while retaining the cellular response to cytokines with anti-tumor activity is a particular advantage that will be optimized in future pre-clinical studies." (PMID 20576164, 2010). "The cells expressing pStat3 and total Stat3 within the Stat3sh tumors were principally non-tumor cells." (PMID 20929542, 2010). "Since Stat3 occupies a central node for many converging signaling pathways, excessive Stat3 activity in tumours can result from oversupply of (IL6-family) cytokines and other growth factors within the tumour microenvironment." (PMID 20478049, 2010). "The physical contact between tumour and antigen presenting cells also directly activates Stat3 and triggers a tolerogenic DC phenotype." (PMID 20478049, 2010). "To determine the consequence of the IL-6 and TGF-β increment, we investigated the cytokine-coupled transcriptional factor signals of STAT3 and Smad3 which were identified as important factors responsible for malign tumor progress." (PMID 20520770, 2010). "This activity is likely to account for the addiction to STAT3 observed in many tumours, displaying a variety of abnormally activated oncogenic pathways that share the ability to induce STAT3 tyrosine phosphorylation and aerobic glycolysis." (PMID 21084727, 2010). "Consistent with the current understanding of STAT3 signalling pathways, predominant nuclear immunostaining of phosphorylated STAT3 was observed in the vehicle-treated control tumours (upper left)." (PMID 20461084, 2010). "In this review we focus on Stat3, because it provides a central signaling node for neoplastic cells to induce transcriptional responses which promote tumour growth." (PMID 20478049, 2010). "IL-6 mRNA was found to be elevated in tumor tissue in gp130 mutant mice with abnormally activated Stat3." (PMID 21122157, 2010). "More than other transcription factors, nuclear factor-kappaB (NF-κB) and STAT3 have emerged as major regulators of inflammation, cellular transformation, and tumor cell survival, proliferation, invasion, angiogenesis, and metastasis." (PMID 22069560, 2010). "A comprehensive understanding of the gp130/Stat3 signaling cascade holds great promise to identify and validate therapeutic targets that simultaneously restrict the effect of tumour promoting inflammation while restoring anti-tumour immunity." (PMID 20478049, 2010). "The Jak/Stat3 signaling pathway plays a vital role in regulating a number of pathways in tumorigenesis, including cell cycle progression, apoptosis, tumor angiogenesis, and tumor cell evasion of the immune system." (PMID 20482858, 2010).
tumor (continued). "Not only can Stat3 increase NFkB activity in tumors, but activation of Stat3 in immune cells in the tumor is dependent on NFkB and IL-6 which is downstream from NFkB." (PMID 20885960, 2010). "Very recently, hTERT has been identified as a direct downstream gene of STAT3 in both tumor and normal cells." (PMID 20723213, 2010). "These properties are of importance based on recent murine studies showing the Jak2 inhibitor WP1193 can augment immunotherapy with IFN-α, and STAT3 siRNA-CpG oligodeoxynucleotides can elicit anti-tumor immune responses." (PMID 20576164, 2010). "In contrast with the induction of Foxp3+ Treg cells in the periphery, there is evidence that in the tumor microenvironment, STAT3 signaling through IL-23R expression increases Foxp3 and IL-10 expression by Treg cells." (PMID 20732640, 2010). "Studies using tumor cells have shown that the expression of IL13RA2 up-regulates that of STAT3, which ultimately compromises the IL-13 signal." (PMID 21179488, 2010). "We previously demonstrated that AS2 cells produced autocrine IL-6 and the secreted IL-6 induced Stat3 activation and subsequently promoted tumor progression." (PMID 21122157, 2010). "We propose that this novel, central metabolic role is at the core of the addiction for STAT3 shown by so many biologically different tumours." (PMID 21084727, 2010). "We focus on the various feed-back and feed-forward loops in which Stat3 provides the signaling node in cells of the tumour and its microenvironment thereby functionally linking excessive inflammation to neoplastic growth." (PMID 20478049, 2010). "By contrast, Stat3 ablation in intestinal epithelium in vivo or in tumour cell lines in vitro resulted in cell cycle arrest in the G2/M transition and is associated with histone H3 phosphorylation-associated mitotic arrest." (PMID 20478049, 2010). "STAT3 plays central roles in most cancer hallmarks including tumor cell survival, proliferation, angiogenesis, metastasis, and immune evasion." (PMID 24281185, 2010). "Stat3 is an oncogene that is constitutively active in many tumor types and promotes cell proliferation and survival." (PMID 20482858, 2010). "Sunitinib inhibits Stat3 in both tumor cells and tumor myeloid cells, thereby leading to tumor cell apoptosis and reduced expression of angiogenic genes and immunosuppressive cells." (PMID 20819239, 2010). "In other malignancies, it has been suggested that the Stat3 signalling pathway regulates tumour progression by regulating downstream genes crucial to angiogenesis, proliferation, invasion, and immune evasion." (PMID 19638983, 2009). "Blocking signalling to STAT3 by dominant-negative (DN) STAT3 mutant or antisense STAT3 oligonucleotides inhibits cancer cell growth, showing that STAT3 is crucial to the survival and growth of tumour cells." (PMID 19127268, 2009). "We demonstrate that in addition to tumor-derived secreted factors tumor cells activate STAT3 by a mechanism that is based on cell-cell interaction." (PMID 19718269, 2009). "Downregulation of both Stat3 activity and expression of Stat 3-controlled pro-survival proteins, contributes to the induction of apoptosis in avicin treated tumor cells." (PMID 19440292, 2009). "The SP1, MAX, RUNX1 and STAT3 sub-networks are involved in both early and late stages of the tumor but are expressed with different gene expressions." (PMID 20025723, 2009). "Stat3 forms a nodal point of an assembly of proteins that regulate wounding, chronic injury, inflammation, and tumor cell survival." (PMID 19440292, 2009). "In the current study, by simply washing the cells just prior to adding the APC we eliminated the contribution of tumor-secreted factors, thereby revealing the contact-dependent activation of STAT3." (PMID 19718269, 2009). "The overall survival rate was significantly higher in patients with p-Stat3-negative tumours than in those with p-Stat3-positive tumours (P=0.006; log-rank test)." (PMID 19638983, 2009).